SGTB (small glutamine rich tetratricopeptide repeat co-chaperone beta)
Description:
Co-chaperone that binds directly to HSC70 and HSP70 and regulates their ATPase activity.
Synonyms: SGT2; FLJ39002
Tractability: PROTAC: ubiquitination databases record sites on it; its protein half-life has been measured.
Gene: Protein-coding gene on chromosome 5 (65,665,928 to 65,723,035, reverse strand). Ensembl gene ENSG00000197860.
Subcellular location (Human Protein Atlas): Nucleoplasm; Primary cilium; Basal body; Microtubules; Nuclear speckles
Gene Ontology:
Molecular function: protein binding; molecular adaptor activity; Hsp70 protein binding; identical protein binding; protein-folding chaperone binding
Biological process: post-translational protein targeting to endoplasmic reticulum membrane; protein heterooligomerization; protein homooligomerization
Cellular component: membrane; TRC complex
Genetic constraint (gnomAD): Loss-of-function variants: 13 observed, 37.2 expected, observed/expected ratio (o/e) 0.35, 90% interval 0.23 to 0.56. The upper end of that interval is the gene's LOEUF score, 0.56, which puts it in group 2 of 6, group 1 being the genes least tolerant of losing a copy. Missense variants: 283 observed, 356.32 expected, observed/expected ratio (o/e) 0.79, 90% interval 0.72 to 0.88. Synonymous variants: 109 observed, 119.63 expected, observed/expected ratio (o/e) 0.91, 90% interval 0.78 to 1.07.
Homologues: Orthologues: chimpanzee SGTB (99% identical), macaque SGTB (99% identical), rabbit SGTB (97% identical), dog SGTB (96% identical), mouse Sgtb (96% identical), pig SGTB (96% identical), rat Sgtb (96% identical), guinea pig SGTB (92% identical), tropical clawed frog sgtb (74% identical), zebrafish sgtb (73% identical), Drosophila melanogaster unc-45 (13% identical), Caenorhabditis elegans unc-45 (12% identical). Paralogues in human: SGTA (60% identical), RPAP3 (21% identical), SPAG1 (20% identical), TTC4 (19% identical), SPATA16 (17% identical), ST13 (17% identical), STUB1 (17% identical), TTC1 (17% identical), STIP1 (16% identical), UNC45A (16% identical), UNC45B (15% identical), DNAAF4 (15% identical), and 6 more.
Diseases named in the same sentence as SGTB in open-access papers:
SGTB is named in the same sentence as 11 diseases in open-access papers, as found by Europe PMC text mining. Sharing a sentence is not in itself a finding about the gene and the disease. The quoted sentences say what the papers report.
coronary artery disease (1 paper, 2025). "Both SGTB and HTRA1 were downregulated in the aorta of patients with coronary artery disease compared with controls." (PMID 41190437, 2025).
COVID-19 (1 paper, 2022). A disease caused by infection with severe acute respiratory syndrome coronavirus 2. "Conversely, for most of the other genes (7 out of 9) in this superset, downregulation correlated increased HRs of COVID-19 mortality, including two genes (SEC62 and SGTB) that target ER and participate in degradation of misfolded proteins." (PMID 35547187, 2022).
osteoarthritis (1 paper, 2022). A noninflammatory degenerative joint disease occurring chiefly in older persons, characterized by degeneration of the articular cartilage, hypertrophy of bone at the margins and changes in the synovial membrane. "HOTAIR modulates chondrocyte apoptosis and inflammation in osteoarthritis via the regulation of the miR-1277-5p/SGTB axis." (PMID 35626352, 2022).
Takayasu arteritis (1 paper, 2018). A rare inflammatory large-vessel vasculitis primarily affecting the aorta and its major branches, but also other large vessels, causing stenosis, occlusion, or aneurysm. "In CD8+ cells, two transcripts remained differentially expressed after 12 months; SGTB, associated with neuronal apoptosis, and FCGR3A, associatied with Takayasu arteritis." (PMID 30037347, 2018).
type 2 diabetes (1 paper, 2025). "Consistent with effects of damaging variants in HTRA1, SGTB, and RBM12 acting independently of traditional cardiovascular risk factors, these associations persisted after adjusting for LDL cholesterol, smoking, type 2 diabetes, body mass index, and systolic blood pressure." (PMID 41190437, 2025).
cardiovascular disease (1 paper, 2025). "While RBM12 was not differentially regulated in the aorta from patients with cardiovascular disease, SGTB was significantly downregulated (false discovery rate–corrected P=2.1×10−5)." (PMID 41190437, 2025).
infection (1 paper, 2023). The state of being infected such as from the introduction of a foreign agent such as serum, vaccine, antigenic substance or organism. "Although glyS and sgtB roles in cell wall synthesis in S. aureus are well defined, their involvement in cell wall protection during host infection and persister cell formation remained obscure." (PMID 37901830, 2023).
SGTB also shares sentences with these, for which no sentence is quoted: atherosclerosis (1 paper); cancer (1); hepatocellular carcinoma (1); psychosis (1).